Y_RNA (Y RNA )
Gene: Miscellaneous RNA gene on chromosome X (40,492,844 to 40,492,941, forward strand). Ensembl gene ENSG00000206677.
Homologues: Orthologues: chimpanzee Y_RNA (99% identical). Paralogues in human: Y_RNA (88% identical), RNY3 (87% identical), Y_RNA (87% identical), Y_RNA (86% identical), RNY3P1 (85% identical), Y_RNA (85% identical), RNY3P11 (84% identical), Y_RNA (84% identical), Y_RNA (83% identical), RNY3P14 (82% identical), Y_RNA (82% identical), RNY3P2 (81% identical), and 93 more.